DAB2IP (DAB2 interacting protein)
Diseases named in the same sentence as DAB2IP in open-access papers (continued):
Sharing a sentence is not in itself a finding about the gene and the disease.
tumor (continued). "The tumor-suppressor DAB2IP (Disabled homolog 2 interacting protein) plays an important role in this context, since it modulates cell responses to multiple extracellular inputs, including inflammatory cytokines and growth factors." (PMID 38902547, 2024). "In line with the effects of its depletion or inhibition, several studies over the past 20 years confirmed that DAB2IP overexpression dampens cancer cell growth, metastasis and stem cell phenotypes, in different tumor types." (PMID 38902547, 2024). "Transfection of an anti-miR-1307-3p repressed HCC proliferation and invasion in vitro and tumor growth in vivo; importantly the effect was abrogated in DAB2IP knockdown cells, confirming its dependency on DAB2IP upregulation." (PMID 38902547, 2024). "In PCa cells, DAB2IP inhibited expression of stem cell factor receptor c-kit (or CD117) reducing the capability to generate tumor spheres in vitro." (PMID 38902547, 2024). "Multiple mechanisms of DAB2IP inactivation have been observed in cancer, suggesting that tumor cells take advantage from the inhibition of such a protein that negatively modulates several oncogenic signaling pathways." (PMID 38902547, 2024). "DAB2IP mediates tumor suppression ensuring the inhibition of multiple oncogenic pathways, as it has been thoroughly reviewed previously." (PMID 38902547, 2024). "It is worth recalling that DAB2IP is quite unique as a tumor suppressor, since it modulates multiple key pathways aberrantly activated in many cancers." (PMID 38902547, 2024). "In pancreatic cancer, overexpressed DAB2IP increased sensitivity to cetuximab of cancer cells in vitro, and tumor growth in vivo in mouse xenografts." (PMID 38902547, 2024). "DOC-2/DAB2 interactive protein (DAB2IP) is characterized as tumor suppressor and showed critical role in suppressing CSCs properties in some cancer types." (PMID 37443071, 2023). "The tumor suppressor DAB2IP is a Ras-GAP and scaffold protein that negatively modulates multiple oncogenic pathways and is frequently downregulated or inactivated in solid tumors." (PMID 37444489, 2023). "In vivo study showed that the overexpression of circRNA‐5692 suppressed xenograft HCC tumor growth via inhibiting miR‐328‐5p to elevate DAB2IP level, indicating suppressive effects of circRNA‐5692/miR‐328‐5p/DAB2IP network on HCC development." (PMID 36705414, 2023). "DAB2IP plays a role in cell growth inhibition and correlates as a tumor-suppressing gene with the apoptotic process of the CDKN2BAS mechanism pathway." (PMID 37893562, 2023). "DAB2IP is a cytoplasmic protein that negatively modulates several signaling pathways; being a tumor suppressor, it is frequently disabled in cancer." (PMID 37444489, 2023). "circRNA-5692 had been found to inhibit HCC development and EMT progression by accelerating demethylation of the DAB2IP gene and enhancing its expression and circRNA-5692 also acted as a tumor suppressor via the miR-328-5p/DAB2IP pathway." (PMID 38322286, 2023). "In animal models, we validated the DAB2IP protein expression in tumours formed by DAB2IP‐inhibition/overexpression TNBC cells using Western blotting and IHC assay." (PMID 36536485, 2022). "All injections of cells with silenced DAB2IP induced tumour initiation at a concentration of 2 × 104, while two of six injections of control cells failed to initiate tumours." (PMID 36536485, 2022). "Tumour sphere assay indicated that the self‐renewal ability of cells with DAB2IP‐inhibition was weakened by RAC1‐inhibition." (PMID 36536485, 2022). "Conversely, our data showed an increased frequency of tumour initiation in control cells comparing to the frequency in cells with DAB2IP‐overexpression." (PMID 36536485, 2022). "In contrast, the DAB2IP mutant with alanine substitutions of the Thr531 and Thr546 residues increased chromosomal instability in PCa cells and promoted tumor growth in the PCa xenograft model." (PMID 34775484, 2022).
tumor (continued). "Disabled homolog 2 interacting protein (DAB2IP) plays a tumor-suppressive role in several types of human cancers." (PMID 35248066, 2022). "To investigate the association between epigenetic silence of DAB2IP and tumour progression in TNBC, we detected the level of DAB2IP DNA methylation in CSC." (PMID 36536485, 2022). "Tumour‐sphere assay indicated that DAB2IP‐inhibition enhanced and DAB2IP‐overexpression attenuated self‐renewal ability in TNBC cells." (PMID 36536485, 2022). "Consistently, the rate of tumor growth in the DAB2IP-overexpressing group was also considerably slower than that in the vector group." (PMID 35590292, 2022). "As CSC resistance to chemotherapy results in tumour initiation and cancer relapse, we conducted the limiting dilution assay to investigate the influence of DAB2IP on the tumourigenesis of TNBC." (PMID 36536485, 2022). "DAB2IP, also known as a tumor suppressor in ccRCC, has been reported to be epigenetically repressed by EZH2-mediated methylation of lysine 27 in histone H3 (H3K27me3), and also be degraded by SMURF1-mediated ubiquitin-proteasome regulation." (PMID 35562342, 2022). "At a concentration of 2 × 103–102, a lower incidence of tumour initiation was showed in control cells than in cells with DAB2IP‐inhibition." (PMID 36536485, 2022). "DAB2IP is also known to inhibit tumor cell growth in vitro and in vivo, which highlights important properties for anti-cancer therapies." (PMID 33731010, 2021). "Considered a tumor suppressor, EZH2 plays a role in silencing CDH1, FOXC1, DAB2IP, and TIMP3, events linked to metastatic progression." (PMID 34680307, 2021). "Meanwhile, the DOC-2/DAB2 interacting protein DAB2IP was previously identified as a member of the Ras-GTPase activating protein family, and functions as a tumor suppressor in cancer progression." (PMID 32943609, 2020). "More intriguingly, Kaplan‐Meier analysis indicated that the presence of DAB2IP‐positive tumours was significantly correlated with better overall survival of patients (P = 0.003)." (PMID 31713929, 2020). "DAB2IP is a tumor suppressor whose expression and function are altered in multiple human malignancies, causing uncontrolled activation of multiple oncogenic pathways, including Ras, NF-κB, PI3K/Akt, and Wnt/β-catenin." (PMID 33096593, 2020). "On the basis of IHC staining scoring, the DAB2IP was positively expressed in 39.0% (23/59) of GC samples; in contrast, 69.5% (41/59) of the matched tumour‐adjacent tissues exhibited DAB2IP‐positive expression (P = 0.01)." (PMID 31713929, 2020). "Without degradation by Smurf1, DAB2IP negatively regulates downstream pathways, but Smurf1 enhances Ras-MAPK and NF-kB oncogenic pathways by targeting DAB2IP, which bolsters tumor cell proliferation, survival, and migration." (PMID 33718111, 2020). "DAB2IP inhibition by miR-556 in bladder and esophageal cancer fosters cells proliferation and sustains tumor progression via aberrant Ras-MAPK signaling activation." (PMID 33096593, 2020). "Both RASSF1A and DAB2IP are complex tumor suppressors that regulate multiple cellular processes, including growth, apoptosis, and genomic stability." (PMID 33348649, 2020). "We also found that tumours with high miR‐92b status had a significantly lower DAB2IP IHC score than tumours with low miR‐92b status, indicating that miR‐92b expression was inversely correlated with DAB2IP expression." (PMID 31713929, 2020). "The mammalian homologs of Raskol, Rasal2 and Dab2IP, were identified in a screen for RasGAP tumour suppressors and are frequently downregulated in multiple types of cancer cells." (PMID 30763317, 2019). "Immunohistochemical staining confirmed that the expression of DAB2IP is downregulated in tumor tissues and is further reduced in those with lymph node metastasis." (PMID 29743885, 2018). "Increased DAB2IP expression inhibits the growth of several cancer cells, suggesting that it functions as a tumor suppressor." (PMID 30602706, 2018).
tumor (continued). "In cancers, downregulation of DAB2IP has been demonstrated to be involved in tumor cell proliferation, apoptosis, metastasis, and epithelial-mesenchymal transition (EMT) through several signaling pathways, including Ras-ERK, PI3K-Akt, ASK1-JNK, and NF-κB." (PMID 29743885, 2018). "In cancer cells, DAB2IP, as a Ras-GTPase, exerted a suppressive effect on tumor invasion and maintained chromosomal stability." (PMID 28962556, 2017). "It has been reported that the DOC-2/DAB2 interactive protein (DAB2IP) is a potent suppressor of PCa tumor progression." (PMID 28081154, 2017). "DAB2IP is considered as a Ras-GTPase activator and a tumor suppressor gene, repressing tumor proliferation and metastasis and maintaining chromosomal stability." (PMID 28962556, 2017). "DAB2IP functions as a tumor suppressor in cancer development with its cell-growth inhibition and pro-apoptosis." (PMID 26658103, 2016). "To further explore the impact of tumor heterogeneity on methylation analysis, we determined DAB2IP CpG1 methylation value of different samples from the same tumor tissue." (PMID 27129174, 2016). "As radiation therapy continues expand its role in bladder cancer (BCa) treatment, DAB2IP shows the similar potent tumor suppressor gene property." (PMID 26658103, 2016). "DAB2IP, a novel family of RasGTPase-activating protein family as a potent tumor suppressor, is epigenetically silenced, which is suppressed by EZH2 and other epigenetic machinery such as DNA methylation and histone acetylation." (PMID 27129174, 2016). "With more and more research available, DAB2IP function is that of a tumor suppressor in tumor cell growth, metastasis, and other aspects in cancer progression." (PMID 26658103, 2016). "These, in turn, have suggests that DAB2IP is a potent tumor suppressor in CRC and it perhaps can be used as prognostic maker and further developed into a curative therapy for CRC." (PMID 26564738, 2015). "DAB2IP expression was inversely correlated with tumor differentiation and metastasis, and patients with lower DAB2IP expression had shorter overall survival time." (PMID 26564738, 2015). "DAB2IP was reduced gradually in the adjunct normal tissue, primary tumor and liver metastatic lesion from the same patient." (PMID 26564738, 2015). "The present study established for the first time the important role played by miR-32 in inhibiting the expression of the DAB2IP tumor suppressors in PCa." (PMID 26622795, 2015). "Mechanistic studies showed that after T cells migrated toward RCC cells, both ERβ transcriptional activity and protein expression increased, but DAB2IP, a tumor suppressor gene, decreased." (PMID 26587829, 2015). "In the mouse models of tumor growth and metastasis, Snail KD cells and Snail/DAB2IP KD cells were injected in subcutaneous site of nude mice or into tail vein to seed lung metastases, respectively." (PMID 26336990, 2015). "Pretreatment tumor reduction in DAB2IP as evidenced by prostate biopsy samples correlated strongly with worse outcome in every endpoint measured except death from any cause." (PMID 26471467, 2015). "In the present study, it was found that DAB2 interacting protein (DAB2IP), the miR-32-dependent tumor-suppressor gene, was downregulated and induced autophagy and inhibited radiotherapy-induced apoptosis in PCa cells." (PMID 26622795, 2015). "Downregulation of DAB2IP, mainly due to epigenetic regulation, inversely correlates with tumor grade and predicts PCa progression." (PMID 26622795, 2015). "Unexpectedly, DAB2IP KD enhanced subcutaneous tumor growth and correspondingly increased cell proliferation labeled by Ki67 index." (PMID 26336990, 2015). "In this study, we first identify that DAB2IP functions as a tumor suppressor in the progression of CRC." (PMID 26336990, 2015). "One limitation of this study includes the way in which tumor DAB2IP status is characterized as reduced or retained." (PMID 26471467, 2015).
tumor (continued). "Pretreatment tumor DAB2IP status remained significant in the multivariable analysis for FFBF (P = 0.0026), CRFS (P = 0.0043), and DMFS (P = 0.0009)." (PMID 26471467, 2015). "Deletion of ovarian carcinoma 2/disabled homolog 2 (DOC-2/DAB2) interacting protein (DAB2IP), has been described as a tumor suppressor in various types of cancer." (PMID 24912918, 2014). "Recent studies have indicated that DAB2IP down-regulation has implications in resistance to ionizing radiation, initiation of the epithelial-to-mesenchymal transition and promotes tumor growth and metastasis." (PMID 24912918, 2014). "DAB2IP has roles in both tumor initiation and metastasis, whereby DAB2IP controls primary tumor growth through activating Ras and drives metastasis through controlling NF-κB through regulation of TRAF2." (PMID 24912918, 2014). "Deletion of ovarian carcinoma 2/disabled homolog 2 (DOC-2/DAB2) interacting protein (DAB2IP), is a tumor suppressor that serves as a scaffold protein involved in coordinately regulating cell proliferation, survival and apoptotic pathways." (PMID 24912918, 2014). "Given that DAB2IP is a potent tumor suppressor, and is down-regulated in a variety of human tumors, we intend to determine if DAB2IP is actively regulated by proteasome-mediated degradation in addition to being functionally regulated by phosphorylation." (PMID 24912918, 2014). "DOC-2/DAB2 interactive protein (DAB2IP) is a potent tumor suppressor in PCa, modulating several pathways including that of mitogen-activated protein kinase and phosphoinositide 3-kinase/protein kinase B (Akt)." (PMID 25015118, 2014). "Recent studies have shown that, in addition to its tumor suppressive role in various tumors, DAB2IP also plays an important role in regulating neuronal migration and positioning during brain development." (PMID 24073285, 2013). "Dab2ip (DOC-2/DAB2 interacting protein) is a member of the Ras GTPase-activating protein (GAP) family that has been previously shown to function as a tumor suppressor in several systems." (PMID 23056358, 2012). "DAB2IP is a member of the Ras GTPase-activating gene family and has been reported to act as a tumor suppressor." (PMID 22737080, 2012). "DOC-2/DAB2 interactive protein (DAB2IP) is a novel identified tumor suppressor gene that inhibits cell growth and facilitates cell apoptosis." (PMID 22046421, 2011). "Disabled homolog 2-interacting protein (DAB2IP) is a Ras GTPase-activating protein that serves as a tumor suppressor." (PMID 24213111, 2011). "By partially abolishing these mimic effects, our results not only underscored the importance of DAB2IP in modulating cancer cell behaviour but also pointed to potential therapeutic strategies that could target this pathway to inhibit tumour growth and spread." (PMID 40263693, 2025). "DAB2IP is a tumor suppressor that restrains ERK/AKT/NF-κB signaling and EMT across cancers." (PMID 41374987, 2025). "Lastly, DAB2IP (Disabled homolog 2–interacting protein) is a tumor suppressor that restrains PI3K–AKT, NF-κB, and ERK signaling, regulating apoptosis, epithelial–mesenchymal transition (EMT), and invasion across various cancers, including prostate, colorectal, and gastric." (PMID 41374987, 2025). "Collectively, these findings highlight the multifaceted functions of DAB2IP in cellular processes, ranging from tumor suppression and signal transduction to cell cycle regulation and inflammation, underscoring its importance in maintaining cellular homeostasis." (PMID 41261855, 2025). "Regardless of the mechanism, it is reasonable to speculate that increased DAB2IP levels may support and reinforce the anti-tumor effects of thiostrepton, possibly through synergy with its other molecular targets in a context-dependent manner." (PMID 40867592, 2025). "In BCa, DAB2IP acts as a tumor suppressor by inhibiting the RAS and PI3K/Akt pathways." (PMID 40361412, 2025).
tumor (continued). "Notably, the altered secretome of DAB2IP-depleted cancer cells also affects tumor vascularization, with implications for aggressiveness." (PMID 38902547, 2024). "DAB2IP expression was detected in 95% of normal kidney tissues, while it was decreased in 54% of tumor tissues in the patient cohort, suggesting gene silencing in tumor tissues." (PMID 39051186, 2024). "Less is known about the potential role of DAB2IP in non-transformed cells of the tumor stroma, but there is clear evidence that its loss in endothelial cells (EC) promotes neo-vascularization and angiogenesis." (PMID 38902547, 2024). "Intriguingly, some observations suggest that downregulation of DAB2IP in cells of the tumor stroma could foster establishment of a pro-metastatic microenvironment." (PMID 38902547, 2024). "A better understanding of the role of DAB2IP in immune cells may offer useful insights on its potential in modulating the tumor immune environment." (PMID 38902547, 2024). "Stratification of tumor subtypes based on DAB2IP expression." (PMID 39418101, 2024). "Finally, the BRINP1 (BMP/retinoic acid inducible neural specific 1) gene is associated with hair-greying processes in humans, while the DAB2IP (DAB2 interacting protein) gene has been reported to play a role in tumour suppression and metastasis." (PMID 39199954, 2024). "Preventing DAB2IP phosphorylation by AKT may thus be a strategy to restore its tumor-suppressive function." (PMID 38902547, 2024). "DAB2IP functions as a tumor suppressor for a variety of tumors." (PMID 38322286, 2023). "DAC treatment increased DAB2IP expression in chemoresistant tumours." (PMID 36536485, 2022). "The expression of wild-type DAB2IP totally abrogated tumor growth." (PMID 34775484, 2022). "We further investigated whether DNA methylation leads to DAB2IP low expression and confers aggressive tumour features in TNBC." (PMID 36536485, 2022). "Tumours treated with DAC exhibited increased expression of DAB2IP." (PMID 36536485, 2022). "Both KLF9 and DAB2IP were reported to be tumor suppressors in many tumors." (PMID 34116691, 2021). "Notably, DAB2IP functioned as a signaling scaffold coordinating tumor growth and metastasis by RAS and NF‐κB respectively." (PMID 33599076, 2021). "In addition, the DAB2-interacting protein (DAB2IP) is a tumor-suppressor gene that blocks various survival-essential signaling pathways like PI3K/AKT, AR, JAK/STAT, and Wnt." (PMID 34298665, 2021). "Alternatively, loss of a RasGAP may not be sufficient to induce cell transformation, but can amplify oncogenic signaling pathways, favoring tumor progression in response to aberrant environmental inputs, as probably occurs with DAB2IP and other GAPs." (PMID 33096593, 2020). "For example, phosphorylation of Smurf1 on Thr145 is not important for DAB2IP binding, Smurf1-mediated degradation of DAB2IP, or modulation of Smad1, but it does cause Smurf1 abundance and structural stability, which further increases the degradation of DAB2IP, resulting in tumor progression." (PMID 33718111, 2020). "DAB2IP expression in transfected tumours was detected via IHC and Western blotting." (PMID 31713929, 2020). "We speculated that RASSF1A and DAB2IP might form a tumor suppressor complex that acted in part by regulating RAS-GTP levels." (PMID 33348649, 2020). "DAB2IP is a tumor suppressor itself and acts, in part, as a negative regulator (GAP) for RAS." (PMID 33348649, 2020). "However, co-suppression of RASSF1A and DAB2IP significantly enhanced tumor growth compared to control H1437 cells." (PMID 33348649, 2020). "We further found that miR-328-5p targeted the DAB2IP, one tumor suppressor, because miR-328-5p expression was inversely associated with DAB2IP expression in HCC tissues and cells, and miR-328-5p overexpression mitigated the DAB2IP-regulated luciferase activity." (PMID 31776329, 2019). "Tumor xenografts of 3D HT29 also showed reduced DAB2IP compared with those of 2D HT29." (PMID 30770783, 2019).